NECTIN1 (nectin cell adhesion molecule 1)
Diseases named in the same sentence as NECTIN1 in open-access papers (continued):
Sharing a sentence is not in itself a finding about the gene and the disease.
breast cancer (10 papers, 2012 to 2025). A primary or metastatic malignant neoplasm involving the breast. "Similar to gastrointestinal cancers, breast cancer also shows a trend where a high nectin-1 expression is associated with a higher frequency of metastases." (PMID 40244005, 2025). "Interestingly, despite being an adhesion molecule, nectin-1 expression is associated with metastatic disease in human breast cancer and in highly migratory and invasive squamous cell carcinoma." (PMID 30224769, 2018). "hsa-miR-661 is known to be expressed at early time points of SNAI1-induced EMT and promote invasion of breast cancer cells by degrading two target genes, NECTIN1 (cell-cell adhesion protein), and STARD10 (lipid transferase)." (PMID 28793339, 2017). "In breast cancer metastatic tumors have increased expression of nectin-1 and nectin-2." (PMID 30759143, 2019). "Similarly, the suppression of nectin-1 reduced the levels of cytokeratins-18, beta-catenin, claudine-3 and E-cadherin expression in breast cancer cell lines." (PMID 25690753, 2015). "In another study, Vetter and coworkers showed that miR-661 expression in MCF7 breast cancer cells conditionally overexpressing the EMT master regulator SNAI1 contributes to breast cancer cell invasion by targeting cell-cell adhesion Nectin-1 and the lipid transferase StarD10 messengers." (PMID 22408395, 2012). "miR-661 is shown to regulate Nectin-1 and StarD10 in the disassembly of epithelial cell junctions in SNAI1-expressing breast cancer cells." (PMID 26512777, 2015).
cleft palate (7 papers, 2009 to 2026). Cleft palate is a fissure type embryopathy that affects the soft and hard palate to varying degrees. "This cooperative role of E- and P-cadherin may parallel that seen between Nectin1 and Nectin4 during palatogenesis, where loss of both adhesion proteins resulted in a severe cleft palate while cleft palate was seen with low penetrance in single knockdowns." (PMID 41231213, 2026). "Individuals with cleft lip/palate-ectodermal dysplasia syndrome (OMIM:225060) have distinctive facial features including an underdeveloped lower jaw39, which is consistent with the facial segment (chin) where the NECTIN1 association was observed." (PMID 33436952, 2021).
ectodermal dysplasia (6 papers, 2014 to 2023). "Cleft lip/palate-ectodermal dysplasia syndrome is a rare, autosomal recessive disorder caused by homozygous loss-of-function mutations of the PVRL1 (poliovirus receptor-like 1) gene encoding nectin-1." (PMID 29772684, 2018). "Mutations in nectin-1 gene cause cleft lip/palate ectodermal dysplasia, Margarita Island ectodermal dysplasia, and Zlotogora–Ogür syndrome, which is characterized by cleft lip/palate, syndactyly, intellectual disability, and ectodermal dysplasia." (PMID 36568980, 2022). "Mutations in the human nectin-1 gene are responsible for cleft lip/palate ectodermal dysplasia, Margarita Island ectodermal dysplasia, and Zlotogora–Ogür syndrome, which is characterized by cleft lip/palate, syndactyly, intellectual disability, ectodermal dysplasia, and partial deafness." (PMID 36568980, 2022). "In fact, a mutation in nectin 1 (PVRL1) causes an autosomal recessive ectodermal dysplasia (CLPED1) characterized by OFC, syndactyly, and ectodermal dysplasia." (PMID 31652793, 2019).
glioma (6 papers, 2013 to 2025). A benign or malignant brain and spinal cord tumor that arises from glial cells (astrocytes, oligodendrocytes, ependymal cells). "Supporting this supposition is the increased nectin-1 expression seen in pediatric embryonal tumors, which have an even greater likelihood of metastasizing than pediatric glial tumors." (PMID 30224769, 2018). "We demonstrated that oHSV was unable to effectively enter and infect glioma xenograft cells with <20% nectin-1 expression." (PMID 23450706, 2013). "Furthermore, the pediatric embryonal tumors expressed significantly more nectin-1 compared to the pediatric glial tumors (92.6 ± 6.9% versus 67.2 ± 10.2%; p = 0.0014)." (PMID 30224769, 2018). "M032 is an HSV-1 virus genetically engineered to infect glial tumors, largely through binding oHSV to CD111 (nectin-1) expressed on the tumor cell’s surface." (PMID 35342877, 2021). "For in vivo efficacy studies, two pediatric tumors, glial tumor D456 with lower nectin-1 expression and embryonal tumor X21415 with higher nectin-1 expression, and two adult tumors, UAB1066 with lower nectin-1 expression and GBM-12 with higher nectin-1 expression were tested." (PMID 30224769, 2018). "However, this is inconsistent with our results, as there was no significant change in nectin-1 expression when treated with panobinostat in glioma A172 and squamous cell carcinoma SCC9 cells." (PMID 36560800, 2022).
hepatocellular carcinoma (6 papers, 2022 to 2025). A malignant tumor that arises from hepatocytes. "Lastly, NECTIN1 plays a crucial role in modulating immune responses by interacting with various immune cells, and its ex-pression is linked to disease progression in conditions such as hepatocellular carcinoma." (PMID 40971385, 2025). "The expression of nectin-1 in five hepatoma cell lines (SK-Hep-1, Hep 3b, RBE, Huh-7, and PLC/PRF/5) was detected by fluorescence quantitative PCR." (PMID 36059705, 2022). "Further experiments in vivo should be performed to explore the role of nectin-1 in the metastasis of hepatocellular carcinoma in an animal model." (PMID 36059705, 2022). "The average ΔCT values of nectin-1 (nectin-1-ACTB) in the five hepatoma cell lines were 11.42 ± 0.176, 10.09 ± 0.087, 10.69 ± 0.200, 9.50 ± 0.217, and 10.34 ± 0.302, respectively (the abundance of gene expression was high in the cell when the ΔCT value was ≤12)." (PMID 36059705, 2022). "This study showed that nectin-1 mRNA was highly expressed in hepatoma cell lines." (PMID 36059705, 2022). "The proliferation of hepatoma cells decreased after KD of nectin-1." (PMID 36059705, 2022). "We showed that VSV/BVpv could infect not only Vero cells and nectin-1-expressing CHO-K1 cells, but also various other cell lines, such as Huh7 (human hepatoma), BHK-21 (baby hamster kidney), and IMR-32 (human neuroblastoma) cells." (PMID 38847539, 2024). "However, there was no significant change in the proliferation of hepatoma cells after the OE of nectin-1, which may be related to the high background expression of nectin-1 in hepatoma cells." (PMID 36059705, 2022).
colorectal cancer (5 papers, 2021 to 2025). A primary or metastatic malignant neoplasm that affects the colon or rectum. "Nectin-1 expression in colorectal cancer is associated with a significantly worse three-year progression-free survival, therefore, identifying a group of patients at high risk of an early recurrence of the disease." (PMID 36553083, 2022). "In colorectal cancer, Nectin1 expression was associated with a worse 3-year progression-free survival rate." (PMID 34625065, 2021). "In the context of cancer research, one study reported that Nectin1 expression was associated with shorter progression-free survival of colorectal cancer patients." (PMID 34625065, 2021). "Most frequently, the literature describes studies on changes in nectin-1 expression in gastrointestinal cancers (pancreatic and colorectal cancers)." (PMID 40244005, 2025). "However, data regarding the microenvironment and nectin-1 expression are inconsistent, as studies on other cancers, such as colorectal cancer, do not indicate any correlation between nectin-1 expression in the tumor microenvironment and clinicopathological parameters." (PMID 40244005, 2025).
metastatic disease (5 papers, 2013 to 2023). "The elevated expression of nectin-1 implied poorer survival and nectin-1 was the only nectin which was increased in metastatic disease." (PMID 37568798, 2023). "There was increased expression of Nectin-1/-2 in patients with metastatic disease, Nectin-3/-4 was reduced." (PMID 24386110, 2013).
neuroblastoma (5 papers, 2013 to 2025). Neuroblastoma (NB) is the most common solid, extracranial childhood tumor. "An important, novel aspect of the current study was the investigation of CD111 (nectin-1) in human neuroblastoma cell lines and human tumor tissues." (PMID 24130898, 2013). "Until our study, there has been only a single report addressing the expression of nectin-1 in human neuroblastoma cell lines." (PMID 24130898, 2013). "Krummenacher and colleagues in 2000 reported that nectin-1 was present on the cell surface of two neuroblastoma cell lines, IMR5 and SY5Y, as documented by FACS analysis." (PMID 24130898, 2013).
squamous cell carcinoma (5 papers, 2013 to 2022). A carcinoma arising from squamous epithelial cells. "Previous studies on Nectin-1 have concentrated on its role in sensitivity to herpes oncolytic therapy in squamous cell carcinoma, thyroid cancer and head/neck carcinoma." (PMID 24386110, 2013). "In squamous cell carcinoma, higher expression of the cell surface adhesion molecule nectin-1 correlated with increased HSV-1 infection and cytotoxicity compared to cells that had lower nectin-1 levels." (PMID 28536385, 2016).
brain tumors (4 papers, 2018 to 2023). "Recently, Nectin-1 was reported to predict the response of brain tumor xenografts to oncolytic HSV-1 infection." (PMID 34205379, 2021). "In brain tumor xenografts, the expression of HSV-1 entry receptor Nectin-1 (HVEC, CD111) was associated with tumor regression." (PMID 34205379, 2021). "The heterogeneity of nectin-1 expression seen between different brain tumor histopathological types and among tumors of the same histology in this study and other studies also support the possible role of nectin-1 as a biomarker for oHSV studies." (PMID 30224769, 2018). "Freshly disaggregated cells from the panel of patient-derived pediatric high-grade brain tumors and adult glioblastoma were evaluated for expression of nectin-1 by flow cytometry." (PMID 30224769, 2018). "In so doing we found that pediatric brain tumors were more sensitive to the viruses and expressed significantly more nectin-1 (CD111) than adult glioblastoma." (PMID 30224769, 2018). "Importantly, nectin-1 expression correlated with the sensitivity of the brain tumor xenografts to G207 and M002." (PMID 30224769, 2018). "Our results suggest that pediatric brain tumors are ideal targets for oHSV and that brain tumor expression of nectin-1 may be a useful biomarker to predict patient response to oHSV." (PMID 30224769, 2018). "Pediatric brain tumors have a greater propensity to metastasize compared to adult glioblastoma, and therefore, we surmise this may be related to the finding that nectin-1 is found in greater amounts on the pediatric tumors." (PMID 30224769, 2018). "Our finding that nectin-1 expression correlates with sensitivity to oHSV in malignant brain tumor xenografts has significance for current and future oHSV brain tumor trials, as it may represent an important biomarker to predict patient response to treatment with oHSV." (PMID 30224769, 2018). "Nectin-1 expression (CD111; HSV receptor) ranged from 4-76% of adult GBMs and inversely correlated with the IC50s of G207 in adult GBM, including PDX-derived GSCs, and pediatric brain tumors." (PMID 37325516, 2023).
chlamydial infection (4 papers, 2014 to 2019). "Chlamydial infections have been suggested to break down these junctions and disrupt epithelial cell integrity through degradation of nectin-1 and keratin-8 and -18, as well as sequestration of β-catenin and E-cadherin." (PMID 26829550, 2016). "Male nectin-1+/+ and nectin-1-/- mice were rectally infected on day 0 then swabbed using the same technique established for vaginal chlamydial infections." (PMID 27486990, 2016). "Because there is evidence of spread from the female genital tract to the intestine and because some male nectin-1-/- mice were available for infection experiments, we sought to develop a male murine rectal infection model of chlamydial infection." (PMID 27486990, 2016). "Here we demonstrated that the host cell adhesion protein nectin-1, is required for optimal chlamydial infection in the female mouse genital tract." (PMID 27486990, 2016). "Further dissection of nectin-1 functions is warranted, so that we can increase our understanding of the host response to chlamydial infection and provide new and valuable information regarding chlamydia/host cell interactions." (PMID 25414835, 2014). "The reduction in chlamydial infection observed in the female nectin-1-/- mice led us to hypothesize that nectin-1 would also be required for other routes of chlamydial infection." (PMID 27486990, 2016). "Chlamydial infection of nectin-1 knockdown cell lines demonstrated that though nectin-1 is not required for chlamydial inclusion development, inclusions are smaller and contain aberrant chlamydiae when host cell nectin-1 expression is reduced." (PMID 25414835, 2014). "Thus, in the future, we will determine whether nectin-1 is required for rectal chlamydial infections in female mice and whether hormone treatment affects infection outcome." (PMID 27486990, 2016). "Chlamydial infection studies in nectin-1 knockdown (NKD) HeLa cell lines support this hypothesis." (PMID 25414835, 2014). "Through the use of these two models, we have demonstrated that nectin-1 promotes chlamydial infection in the female genital tract but does not appear to contribute to rectal infection in male mice." (PMID 27486990, 2016). "Therefore, we conclude that nectin-1 is not required for rectal chlamydial infection in male mice since the absence of nectin-1 does not inhibit chlamydial infection at any time interval assayed." (PMID 27486990, 2016). "Interestingly, though nectin-1 was required to promote chlamydial infection in the female genital tract, nectin-1 is not required for chlamydial infection in a male mouse rectal infection model." (PMID 27486990, 2016).
gastric cancer (3 papers, 2017 to 2023). A primary or metastatic malignant neoplasm involving the stomach. "In addition, Nectin1 expression was decreased in gastric cancer compared to normal gastric tissue and was associated with better OS." (PMID 34625065, 2021). "Infection of HSV-resistant Chinese hamster ovary (CHO) cells expressing ectopic carcinoembryonic antigen (CEA) and vector alone resistant nectin-1/CEA-harboring human gastric carcinoma cells was successfully demonstrated by this adapter." (PMID 28559846, 2017). "A recent study demonstrated that nectin-1:scFv anti-CEA adapter (soluble bridging molecule) enhances transduction efficacy and produces three times reduction in tumor volume when compared to no adaptor control animals bearing human gastric carcinoma MKN45 tumors in the flank." (PMID 28559846, 2017).
glioblastoma (3 papers, 2018 to 2021). The most malignant astrocytic tumor (WHO grade IV). "M002 also significantly prolonged median survival in mice bearing pediatric glioblastoma D456, which had lower nectin-1 expression." (PMID 30224769, 2018). "To study both of these effects in a mouse model of glioblastoma (GBM), we employed murine GBM cells engineered to constitutively express the type I Herpes Simplex Virus (HSV1) HSV-1 receptor, nectin-1, to allow for more efficient infection and replication by oncolytic HSV (oHSV)." (PMID 32198420, 2020).
ovarian carcinoma (3 papers, 2017 to 2025). A malignant neoplasm originating from the surface ovarian epithelium. "Our previously published studies using ovarian cancer cell lines show that peptide N4-P10 blocks adhesion to the extracellular domain of Nectin-1 in vitro, as do antibodies to Nectin-4." (PMID 40075748, 2025). "The peptides that demonstrated the strongest inhibition of spheroid formation in our live cell imaging assay were among the same peptides with the ability to block ovarian cancer cell adhesion to Nectin-1 in a short-term binding assay." (PMID 32629816, 2020). "To assess the clinical relevance of the cell adhesion molecule Nectin-4 and its binding partner Nectin-1 in ovarian cancer, we examined their RNA expression in patient samples, as well as the human mesothelial cell lines LP9 and Met5a." (PMID 28038455, 2017). "We have also shown that Nectin-4 and its binding partner Nectin-1 are expressed in ascites cells, primary tumors, and omental metastases from ovarian cancer patients, as well as human mesothelial cells." (PMID 28038455, 2017). "In this study we showed that both Nectin-4 and its binding partner Nectin-1 are expressed in ovarian cancer primary tumors, ascites cells and omental metastases from patients, as well as in human mesothelial cells, setting the stage for ovarian cancer cell adhesion in vivo." (PMID 28038455, 2017). "The expression of Nectin-4 on the surface of ovarian cancer tumors suggests that Nectin-4 is a valid target for therapy, and our in vitro data showed that a mAb against the IgV domain of Nectin-4 almost completely blocked ovarian cancer cell adhesion to Nectin-1." (PMID 28038455, 2017). "The second cell line tested was the ovarian cancer cell line, CAOV3, which expresses moderate levels of Nectin-4 protein but very low levels of Nectin-1 protein." (PMID 40075748, 2025). "In contrast, peptide N4-P27 did not inhibit ovarian cancer cell adhesion to recombinant Nectin-1, but was found to inhibit spheroid formation in this study." (PMID 32629816, 2020).
pancreatic cancer (3 papers, 2023 to 2025). "Previous studies have shown a strong association between sensitivity to T-VEC and nectin-1 expression in melanoma and a weak correlation in pancreatic cancer." (PMID 40955425, 2025). "A growing body of evidence suggests that nectin-1 demonstrates prognostic and diagnostic potential in breast, colorectal, and pancreatic cancers." (PMID 40244005, 2025).
Anxiety (2 papers, 2013 to 2022). Intense feelings of nervousness, tension, or panic often arise in response to interpersonal stresses. "In our study, in order to exclude the possibility that the effects elicited by the infusion of the antibody targeting nectin-1 on freezing behavior were confounded by anxiety or locomotor activity, rats were infused with the antibody in the ventral hippocampus and tested in the open field." (PMID 23418609, 2013). "Further control experiments indicated that the effects of ventral hippocampal infusion of the nectin-1 antibody in contextual fear memory cannot be ascribed to memory non-specific effects such as changes in anxiety-like behavior or locomotor behavior." (PMID 23418609, 2013). "Importantly, the lack of effect of blockade of nectin-1 function in the ventral hippocampus in anxiety or locomotion does not imply a lack of involvement of this hippocampal subdivision in these previously proposed functions." (PMID 23418609, 2013).
corneal infection (2 papers, 2012). A viral or bacterial infectious process affecting the cornea. "In support of our findings, nectin-1 knockout studies have demonstrated the loss of corneal infection by HSV-1." (PMID 23213272, 2012). "This study was undertaken to uncover the relative significance of nectin-1 as an entry receptor in corneal infection and HSV-1 spread to the trigeminal ganglia (TG), a site important for HSV-1 latency and recurrent corneal infection." (PMID 23213272, 2012). "To assess the significance of nectin-1, a member of the immunoglobulin superfamily, in primary HSV-1 infection and spread to the TG, we used a murine model of corneal infection and a HSV-1 mutant, KOS(Rid1), which can only use nectin-1 for entry." (PMID 23213272, 2012). "However, recent studies showed that although nectin-1 was more important as an entry receptor into cornea, mice knocked out for both HVEM and nectin-1 were not susceptible to corneal infection by HSV-1." (PMID 22754650, 2012).
cutaneous melanoma (2 papers, 2021 to 2022). A primary melanoma arising from atypical melanocytes in the skin. "Importantly, NECTIN1 deletions were associated with lower overall survival of patients with cutaneous melanoma." (PMID 36229674, 2022).